HIF1A (hypoxia inducible factor 1 subunit alpha)
Diseases named in the same sentence as HIF1A in open-access papers (continued):
Sharing a sentence is not in itself a finding about the gene and the disease.
endometriosis (52 papers, 2011 to 2026). The growth of functional endometrial tissue in anatomic sites outside the uterine body. "Numerous genes implicated in the pathogenic circumstances of endometriosis were shown to be directly regulated at the transcriptional level as a result of the action of HIF-1α stabilized during hypoxia." (PMID 39768184, 2024). "HIF-1A is, therefore, a recognised angiogenic factor in the pathogenesis of endometriosis that causes the necessary neovascularisation of endometriotic lesions in hypoxic environments." (PMID 37174718, 2023). "Determination of genes expression CTNNB1 and HIF1A helps to allocate risk patients with endometriosis where more precise management is needed." (PMID 35012617, 2022). "Among the various pathways implicated in endometriosis, hypoxia plays a specific role in early phases of ectopic endometrial tissue survival induced by factor 1-α (HIF-1α) gene expression that is upregulated in endometriotic tissues." (PMID 35054341, 2022). "In endometriosis, it was found that ectopic lesions demonstrate an increased expression of the HIF-1α monomeric isoform, which is a hallmark of hypoxia, in comparison to a eutopic endometrium." (PMID 34945174, 2021). "MiR-210-3p is a master HIF-1α-responsive hypoxia-associated miRNA that is highly expressed in endometriosis and stimulates cell proliferation via activating STAT328,29." (PMID 30760709, 2019). "Over-expression of ENO1 and HIF1α in CCOC also demonstrates a clinical link to CCOC's association with endometriosis." (PMID 21754983, 2011). "Thus, the HIF-1α/VEGF axis is critical in endometriosis-associated angiogenesis." (PMID 35449709, 2022). "Local hypoxia/oxidative stress factors such as HIF-1α, local immune factors such as TGFβ, and local environmental factors such as matrix density appear to contribute to the development of endometriosis by triggering EMT processes." (PMID 40806587, 2025). "OCCC is frequently linked to endometriosis and characterized by mutations in ARID1A and PIK3CA, hyperactivation of the PI3K/Akt/mTOR pathway, and overexpression of VEGF, HIF-1α, and IL-6." (PMID 41383608, 2025). "Given DDR2′s role in modulating the ECM and promoting invasiveness, it is likely to act synergistically with VEGF and HIF‐1α in driving lesion progression in endometriosis." (PMID 41424583, 2025). "This interplay between DDR2 and HIF‐1α underscores the importance of targeting DDR2 in conjunction with other hypoxia‐related pathways to manage disease progression in endometriosis." (PMID 41424583, 2025). "In a study of 64 in vitro fertilization (IVF) patients (32 with surgically confirmed endometriosis, 32 controls), levels of E-cadherin, N-cadherin and HIF-1α were measured." (PMID 40806587, 2025). "HIF-1α mediates the induction of proangiogenic factors and the development of angiogenesis is a critical step in the establishment and pathogenesis of endometriosis." (PMID 39478503, 2024). "The upregulation of ERβ and the downregulation of ERα observed in endometriosis is regulated at the transcriptional level by HIF-1α." (PMID 38893278, 2024). "Within this microenvironment, upregulation of HIF1A serves as a key driver of endometriosis, activating multiple signaling pathways." (PMID 39135784, 2024). "Collectively, HIF‐1α and mTOR act as a positive and negative regulator of autophagy, respectively, in endometriosis." (PMID 38645639, 2024). "Targeting the HIF-1α protein in endometriosis mice has been shown in several studies to effectively decrease vascular permeability and hence suppress lesion growth." (PMID 39768184, 2024). "We performed ancillary RT-qPCR analysis and confirmed parallel downregulation of HIF1A and miR-210 in baboons with endometriosis." (PMID 37188982, 2023). "Since the pathological function of HIF-1A in endometriosis was discovered in 2007, the relationship between the pathogenesis of the disease and hypoxic stress has become increasingly evident." (PMID 37174718, 2023).
endometriosis (continued). "On the other hand, hypoxic conditions in endometriosis induce HIF1A expression, and HIF1A-mediated angiogenesis is considered to be involved in the development of endometriosis lesions." (PMID 35565252, 2022). "The deprivation of oxygen level also induces the imbalance of estrogen receptors resulting in the accumulation of HIF-1α in the endometriosis lesions." (PMID 35911854, 2022). "Conventional cytogenetics as well as measurement of transcriptional activity of CTNNB1 (β-catenin) and HIF1A (HIF1-α) genes were prospectively studied in 60 endometriosis patients and 50 control group patients." (PMID 35012617, 2022). "Among the 109 mi RNA of the signature, 29 (27%) are associated with the main signaling pathways of endometriosis: PI3K/Akt, PTEN, Wnt/β-catenin, HIF1α/NF κB, and YAP/TAZ/EGFR (Annex S3)." (PMID 35160066, 2022). "Further studies on the pathogenetic mechanisms of the observed differences, involving inflammatory pathways and HIF-1α, especially in the subgroup of patients with endometriosis, are needed." (PMID 34596747, 2022). "In the endometriosis process, circ_0007331 acts as a miRNA sponge for miR-200c-3p and regulates the expression of hypoxia-inducible factor-1α (HIF-1α)." (PMID 36289820, 2022). "Consistent with other studies, the TGF-B pathway is increased in women with endometriosis and the response to hypoxia via HIF1A targets." (PMID 36232817, 2022). "A previous study demonstrated the positive effect of HBOT in reducing the pro-inflammatory cytokine HIF-1α in endometriosis lesions, possibly due to the clearance of HIF-1α molecules in an oxygen-rich environment." (PMID 35911854, 2022). "The inhibition of miR-200c-3p, conversely, reduced the proliferation and invasion caused by circ_0007331 knockdown, confirming that the circ_0007331/miR-200c-3p/HIF-1α axis has an important role in cell proliferation and invasion in endometriosis." (PMID 34638965, 2021). "Through this mechanistic axis, circ_0007331 knockdown, with the cooperation of HIF1A downstream, reduced the proliferation and invasion of primary endometrial cell cultures from women with endometriosis." (PMID 34638965, 2021). "Using immunohistochemistry, endometriosis lesions from mice treated with circ_0007331 shRNA were negative for HIF1A, but mice treated with anti-miR-200c-3p treatment maintained HIF1A expression." (PMID 34638965, 2021). "The second is the hypoxia-inducible factor-1a (HIF1a), which contributes to endometriosis progression by enhancing inflammation, angiogenesis, and other processes." (PMID 33435569, 2021). "Similar to the change of circ_0007331, the mRNA level of HIF‐1α significantly rose in endometriosis." (PMID 32960511, 2020). "We reported the first circRNAs that affects the regulation of HIF‐1α on endometriosis and explored its possible mechanism." (PMID 32960511, 2020). "Our work not only reveals the potential therapeutic targets for future drug interventions in endometriosis, but also provides novel insights for the fine regulation of HIF‐1α in endometriosis." (PMID 32960511, 2020). "Given that the strong connection between HIF‐1α and the adhesion as well as the proliferation of endometrial cells in endometriosis, we explored the effect of circ_0007331 on the expression of HIF‐1α in this disease." (PMID 32960511, 2020). "Recent reports have shown a relationship between the production of VEGF, macrophage migration inhibitory factor (MMIF), hypoxia-inducible factor-1 a (HIF-1α) and the stage of endometriosis, as well as the severity of dysmenorrhea." (PMID 32069859, 2020). "Further quantitative analysis proved that HIF‐1α protein levels in ectopic endometriosis tissues were higher than eutopic endometrial tissues." (PMID 32960511, 2020). "In the present study, we found that both lncRNA‐MALAT1 and autophagy level were up‐regulated in ectopic endometrium from patients with endometriosis, and its expression level correlates positively with that of hypoxia‐inducible factor‐1α (HIF‐1α)." (PMID 30324652, 2019).
endometriosis (continued). "As such, molecular immunohistochemistry shows a high correlation between precursor endometriosis lesions and matched clear-cell adenocarcinomas for expression of HIF1A and phosphorylated mechanistic target of rapamycin kinase (P-mTOR)." (PMID 30087267, 2018). "In this study, SZD significantly reduced the size of ectopic lesions in rats with endometriosis, inhibited cell proliferation, increased cell apoptosis, and reduced microvessel density and HIF-1α expression." (PMID 29636775, 2018). "The ectopic endometria from patients with endometriosis were reported to exhibit a higher proliferation and antiapoptosis as well as elevated expression of HIF-1α." (PMID 29636775, 2018). "In endometriosis, hypoxia stabilizes hypoxia inducible factor-1α (HIF1A) which downregulates dual-specificity phosphatase-2 (DUSP2) directly and indirectly through miR-20a." (PMID 30087267, 2018). "Recent evidence suggests that macrophages play an important role in the pathogenesis of endometriosis and that the hypoxia-inducible factor-1alpha (HIF-1α) may be involved, but when and how are largely unknown." (PMID 41750540, 2026). "Downregulation of miR-22-3p observed in patients may lessen its inhibitory effects on targets like HIF-1α, promoting hypoxia, inflammation, angiogenesis, and endometrial proliferation—all central to endometriosis pathogenesis." (PMID 40429709, 2025). "Compared to controls, patients with endometriosis had lower serum E-cadherin: 107.6 ± 31.9 vs. 137.9 ± 94.5 ng/5 μg protein (p < 0.05); higher N-cadherin: 525.3 ± 214.8 vs. 286 ± 118.6 (p < 0.01), and higher HIF-1α: 540 ± 222 vs. 272 ± 84 (p < 0.001)." (PMID 40806587, 2025). "Likewise, the expression profile of HIF1A in baboons with induced endometriosis was consistent with those of miR-210." (PMID 37188982, 2023). "Additionally, HIF-1α disturbances have been revealed to be present in endometriosis formation and reaction." (PMID 34596747, 2022). "Therefore, HIF1-α-mediated angiogenesis has a critical role in endometriosis-like cancer progression." (PMID 35449709, 2022). "Hypoxia stress potentiates the pro-inflammatory pathways in endometriosis by facilitating the accumulation of inflammatory molecules such as hypoxia-inducible factor-1 alpha (HIF-1α) and nuclear factor kappa beta, which lead to the downstream cascade effect of prostaglandin production." (PMID 35911854, 2022). "In addition to angiogenesis, HIF-1α also promotes endometriotic stroma cell migration and invasion by up-regulating autophagy in endometriosis." (PMID 35449709, 2022). "Additionally, the inhibition of HIF-1α production in a mouse model of endometriosis suppressed the growth of lesions, indicating hypoxia as a potential therapeutic target." (PMID 34945174, 2021). "Moreover, HIF‐1α inhibitors were gradually adopted in the therapeutic strategy for endometriosis like rapamycin, 2‐methoxyestradiol and HDAC inhibitors." (PMID 32960511, 2020). "To further clarify the connection of circ_0007331, miR‐200c‐3p and HIF‐1α in the endometriosis progression, we established endometriosis model mice by implanting mouse endometrial fragments into the abdominal cavity, following treated with circ_0007331 shRNA, shRNA NC and anti‐miR‐200c‐3p." (PMID 32960511, 2020). "LncRNA-MALAT1 via targeting HIF-1α/3-MA/Beclin1 could mediate hypoxia-induced pro-survival autophagy of HESCs in endometriosis." (PMID 32850438, 2020). "The results of in vivo experiments implied that a circ_0007331/miR‐200c‐3p/HIF‐1α axis‐based regulatory pathway might exist in the endometrium of endometriosis, which could aggravate the endometriosis progression." (PMID 32960511, 2020). "A final in vivo experiment confirmed that circ_0007331 knock‐down could suppress the development of endometriosis through down‐regulating the expression of HIF‐1α." (PMID 32960511, 2020).
endometriosis (continued). "This not only provides a potential tool for other researchers to continue to explore the deeper mechanism of HIF‐1α in endometriosis, but also offers a choice for the therapeutic strategy of endometriosis targeting HIF‐1α, which is different from small molecule inhibitors." (PMID 32960511, 2020). "Other commonly used Chinese medicine prescriptions, such as the ShaoFu Zuyu decoction could reduce the size of ectopic lesions in rats with endometriosis, inhibit cell proliferation, promote apoptosis, and reduce microvessel density and HIF-1α expression." (PMID 32210799, 2020). "We then investigated the molecular mechanism of circ_0007331 in endometriosis and found that it may play the regulatory role in endometrial cells by sponging miR‐200c‐3p to regulate the HIF‐1α expression." (PMID 32960511, 2020). "Genistein could regulate estrogen receptor-α and estrogen receptor-β, and reduce the TNF-α, IL-6, VEGF, and HIF-1α levels in ectopic lesions in the endometriosis murine model." (PMID 32210799, 2020). "To investigate whether lncRNA‐MALAT1, HIF‐1α, and autophagy‐associated marker LC3 play a role in endometriosis, we measured their expression in ovarian endometriosis specimens." (PMID 30324652, 2019). "A growing body of evidence suggests that peritoneal local hypoxia play an important role in endometriosis development and progression and the expression of hypoxia‐inducible factor‐1alpha (HIF‐1α) was increased significantly in the development of endometriosis." (PMID 30324652, 2019). "The same trend of HIF-1α and 8-OHdG expression in both stroma and gland implied that these two proteins may be involved in endometriosis progression." (PMID 30760709, 2019). "The increased expression of HIF1A in endometriosis may represent a novel therapeutic target for endometriosis or ovarian cancer." (PMID 30087267, 2018). "In addition, inhibiting the expression of HIF-1α suppressed the growth of lesion in animal models with endometriosis." (PMID 29636775, 2018). "However, previous research mainly focused on the functional study of HIF‐1α in endometriosis." (PMID 32960511, 2020). "We analysed the expression of HIF-1α, a key regulator of hypoxia, and 8-hydroxy-2-deoxyguanosine (8-OHdG), an OS-induced DNA damage marker, in normal endometria, eutopic endometria and ectopic lesions from endometriosis patients and healthy controls using immunohistochemistry." (PMID 30760709, 2019). "HIF-1α, as a transcription factor that could regulate the expression of hundreds of genes under hypoxic conditions, was reported to play an important role in the progression of endometriosis in several studies." (PMID 29636775, 2018). "Compared with untreated endometriosis, terazosin significantly reduced SF-1, PGE2, IL-6, IL-8, TNF-α, VEGF and HIF-1α across compartments (all p < 0.001), comparable to leuprolide (p = 1.000)." (PMID 42123670, 2026). "Within the hypoxic microenvironment characteristic of endometriosis, DDR2 likely acts in synergy with HIF‐1α, enhancing processes such as tissue remodeling and angiogenesis." (PMID 41424583, 2025). "Among angiogenic factors, vascular endothelial growth factor (VEGF), hypoxia‐inducible factor 1α (HIF‐1α), transforming growth factor β1 (TGF‐β1), and matrix metalloproteinases (MMPs) are more essential in the pathogenesis of endometriosis." (PMID 39110084, 2024). "Activates nuclear factor κB (NF-κB) and hypoxia inducible factor (HIF)-1α signalling pathways, increasing cyclooxygenase (COX)-2 expression in endometriosis." (PMID 39596309, 2024). "Transcriptionally incipient endometriosis (TIE), with 26 patients showed increased level of gene mRNA for both, HIF1A and CTNNB1 compared to CG however significantly lower than in second group." (PMID 35012617, 2022). "This group - transcriptionally evident endometriosis (TEE), contained 34 patients from EG where the level of mRNA genes (HIF1A and CTNNB1) were significantly higher compared to the both, CG as well as TIE." (PMID 35012617, 2022).
endometriosis (continued). "The expression levels of HIF‐1α and LC3 in the ectopic endometrium were significantly greater than those in normal endometrium and eutopic endometrium from women with endometriosis." (PMID 30324652, 2019). "The data revealed that increased protein expression of HIF‐1α and total accumulation of LC3‐II were present in ovarian endometriosis samples compared with normal and eutopic endometrium from women with endometriosis." (PMID 30324652, 2019). "We observed this pathway to be activated in endometriosis and LXA4 attenuated the expression of HIF-1α mRNA in endometriotic lesions and PFCs." (PMID 24587003, 2014). "Notably, DDR2 interacts with key signaling pathways that overlap with well‐established therapeutic targets in endometriosis, such as VEGF and HIF‐1α." (PMID 41424583, 2025). "Taken together, DDR2′s dual role in regulating tissue remodeling and inflammation, combined with its interactions with established therapeutic targets like VEGF and HIF‐1α, positions DDR2 as a promising novel target for therapeutic intervention in endometriosis." (PMID 41424583, 2025). "HIF-1α mediates the induction of proangiogenic factors, such as vascular endothelial growth factor (VEGF), an overexpression of which has been observed in the peritoneal fluid of women suffering from endometriosis." (PMID 39478503, 2024). "The tested tissue cell culture of endometriosis (12Z) expressed a high ratio of VEGF-A to TGF-β1, ANG2 to ANG1, and VEGF-A to HIF-1α, which could explain the invasiveness and high migration potential of endometriosis observed in vivo." (PMID 39199545, 2024). "In the studies included in this scoping review, medicinal decoctions containing Hirudo was shown to downregulate the expression of hypoxia-inducible factor 1-alpha (HIF-1α) and reduce the level of vascular endothelial growth factor (VEGF), thereby suppressing the progression of endometriosis." (PMID 33673020, 2021). "Thus, the authors conclude that MMIF, HIF-1α and VEGF expression in serum can be used to assess the stage of endometriosis, as well as the severity of dysmenorrhea." (PMID 32069859, 2020). "Although the positive feedback regulation between ROS and HIF-1α has been proven in many different diseases, their specific interaction in endometriosis has not been determined." (PMID 30760709, 2019). "Other research has suggested that this Guizhi Fuling Wan may reduce of protein levels of HIF-1α and VEGF in ectopic endometrium and eutopic endometrium in endometriosis patients for one month treatment." (PMID 30402122, 2018). "The global expression profile enriched critical pathways already related to the endometriosis condition, such as PI3K signaling via AKT to mTORC1, mTORC1 signaling, TNFA signaling via NFkB, IL6 STAT3 signaling, TGF beta signaling, and hypoxia via HIF1A targets." (PMID 36232817, 2022). "The relationship between level of HIF-1α and CTNNB1 and the potential of endometriosis malignization was not studied yet." (PMID 35012617, 2022). "Peripheral serum levels of TGF-β and soluble markers for hypoxia (HIF-1α) and angiogenesis (VEGF-A, sVEGFR2), significantly increased in adult forms of endometriosis, were similar in adolescents with and without PE (the main vs. comparison groups of this study)." (PMID 39056769, 2024). "However, no changes were observed in hypoxia-inducible factor 1, alpha subunit (HIF1A) expression, suggesting that green tea EGCG has an anti-angiogenic effect in endometriosis, specifically through VEGF suppression." (PMID 34063635, 2021).